ESR1 (estrogen receptor 1)
Diseases named in the same sentence as ESR1 in open-access papers (continued):
Sharing a sentence is not in itself a finding about the gene and the disease.
breast cancer (continued). "It has been reported that the abnormal expression of STAT1, ESR1, CYP1B1, FN1 and UGT1A family genes is closely related to breast cancer and TAM multidrug resistance, while the relationship between AKR1 family and breast cancer and TAM resistance has not been studied." (PMID 34886806, 2021). "Furthermore, we found that E2 treatment did not induce ESR1 and TRIM3 expression in breast cancer." (PMID 34508066, 2021). "Furthermore, an association with various estrogen-dependent genes such as ANXA1, PIWIL2, CASP4, ESR1/ESR2, PLAC1, and SOCS2, has been shown in breast cancer—however, up to date, no such data concerning adenocarcinomas of the esophagogastric junction have been published." (PMID 31467538, 2019). "Furthermore, a significant (p < 0.05) positive correlation between ESR1 and S100A8 and S100A9 gene expression levels was observed in basal breast cancer patients; whereas such a correlation was significantly (p < 0.05) negative in the Her2, Luminal A, and Luminal B types of breast cancer patients." (PMID 39594999, 2024). "For example, miR-4728-3p was reported to target ESR1 (Estrogen Receptor 1) via a non-canonical seed interaction; another report further demonstrated that co-amplification of miR-4278 could protect HER2-positive breast cancers from lapatinib treatment through repressing ESR1." (PMID 33529238, 2021). "In addition to classical nuclear ERα (ESR1) and ERβ (ESR2) acting as ligand-activated transcription factors, it has become evident that non-nuclear ERs govern numerous cell processes in the brain and exert beneficial cardiometabolic effects without uterine or breast cancer growth in mammals." (PMID 33025361, 2020). "However, the expression pattern of QSOX1 correlated with neither ESR1 nor HER2, indicating that quiescin Q6 might be a new prognostic factor suitable for cancer staging and for the further stratification of patients with breast cancer." (PMID 23460839, 2013).
triple-negative breast carcinoma (1,319 papers, 2008 to 2026). An invasive breast carcinoma which is negative for expression of estrogen receptor (ER), progesterone receptor (PR), and human epidermal growth factor receptor 2 (HER2). "Meanwhile, the keywords “cdk4”, “triple negative breast cancer”, “esr1 mutations” and “multicenter” appeared in recent years." (PMID 37637052, 2023). "Emerging topics such as “cdk4”, “triple negative breast cancer”, “esr1 mutations”, and “multicenter” need further research." (PMID 37637052, 2023). "The in vitro induced CDH1 silencing strongly correlates with the promoter methylation of other genes, such as ESR1 (encoding for the estrogen receptor alpha), silenced in a subset of invasive breast cancer (TNBC, triple-negative breast cancer)." (PMID 32806509, 2020). "Triple-negative breast cancer (TNBC) lacks estrogen receptor (ER) α, but the expression of estrogen receptors ERβ and G protein-coupled estrogen receptor 1 (GPER-1) is able to trigger estrogen-responsivity in TNBC." (PMID 33114740, 2020). "Surprisingly, FGD3 mRNA expression in BT-20, a triple-negative breast cancer cell line, was upregulated to 1.99 and ESR1 was upregulated to 0.47 on a log2 scale when treated with an EGFR inhibitor." (PMID 32913979, 2017). "Despite an abundance of estrogen receptor 1 (ESR1) gene transcripts, few fractions transitioned to the triple-negative breast cancer (TNBC) phenotype with a visible loss of ER protein expression and a distinct microRNA expression profile that is reportedly enriched in breast CSCs." (PMID 36834918, 2023). "Triple negative breast cancers (TNBCs) are known to express low PGR, ESR1, and ERBB2, and high KRT5, KRT14, and KRT17." (PMID 30335837, 2018). "The BT549 and MDA-MB-231 cell lines are triple negative breast cancer (TNBC) cell lines, which lack expression of estrogen receptor alpha (ESR1), progesterone receptors, and HER2/neu." (PMID 21501518, 2011). "Interestingly however, samples low in ESR1 topic showed a high FOXM1 topic expression and predominantly consisted of triple negative breast cancer (TNBC) samples." (PMID 36318267, 2022). "Triple-negative breast cancer (TNBC) is diagnosed in cases where tumors are negative for ESR1, PGR, and HER2." (PMID 34408238, 2021). "The triple-negative breast cancer (TNBC) subtype is characterized as negative for the estrogen receptor 1 (ESR1), progesterone receptor (PGR), and human epidermal growth factor receptor type 2 (HER2)." (PMID 32806648, 2020). "The triple-negative breast cancer (TNBC) subtype is characterized as being negative for the estrogen receptor 1 (ESR1), progesterone receptor (PGR), and human epidermal growth factor receptor type 2 (HER2)." (PMID 30050079, 2018). "Triple negative breast cancer (TNBC) comprises a heterogeneous group of tumors defined as a basal-like subtype lacking estrogen receptor alpha (ESR1), progesterone receptor (PGR), and human epidermal growth factor receptor 2 (ERBB2)." (PMID 30123188, 2018). "Therefore, although this study was conducted on triple negative breast cancer, we were able to detect RNA expression of ERBB2 and ESR1, and found a complex expression pattern among HER family members and the ESR1 gene in TNBC." (PMID 26907936, 2016). "Interestingly, the C19MChigh group harbored significantly downregulated expression of PGR, ESR1 and ERBB2 mRNAs compared to C19MClow group, the candidate “negative markers” of triple negative breast cancers." (PMID 30335837, 2018).
breast tumors (1,070 papers, 2003 to 2026). "Recent findings from the EMERALD trial have demonstrated the efficacy of elacestrant in HR+ mBC, particularly within the ESR1 mutated breast tumors." (PMID 40989687, 2025). "Breast tumors with ESR1 mutations displayed increased basal cytokeratins and immunological activation." (PMID 39594999, 2024). "In contrast to secondary resistance, mutations in the ER alpha gene (ESR1) are rare and only found in <1% of treatment-naïve breast tumors." (PMID 38003387, 2023). "In fact, breast tumors harboring ESR1 mutations have demonstrated greater sensitivity to selective estrogen receptor modulators such as tamoxifen and fulvestrant and to the combination of these endocrine therapies with CDK4/6, PI3K, or mTORC1 inhibitors." (PMID 38239650, 2023). "Remarkably, 7 of the top 10 genes in Y537S cells were also overexpressed in human breast tumors with the corresponding ESR1 mutation." (PMID 35881485, 2022). "Across all studies, there were 6 tumors with pathogenic ESR1 mutations identified among 3682 hormone-positive treatment-naïve primary breast tumors." (PMID 35959983, 2022). "As ESR1 mutations are detected in 15–30% of breast tumors, several studies evaluated hotspot ESR1 mutations using ddPCR in the plasma of patients with primary or metastatic breast cancers or with resistance to endocrine therapy." (PMID 36553049, 2022). "We determined the incidence of de novo ESR1 mutations in hormone-positive treatment-naïve primary breast tumors using 12 publicly available international datasets in the cBioPortal." (PMID 35959983, 2022). "The ESR1 PvuII polymorphism was analysed by Sanger sequencing of DNA from primary breast tumour samples." (PMID 34930150, 2021). "The ESR1 gene encodes ERα, which plays central roles in mammary carcinogenesis and clinical response of breast tumors to endocrine therapy." (PMID 34094972, 2021). "Y537S has been shown to be the second most frequently occurring ESR1 mutation in endocrine resistant breast tumors in patients and mutated ESR1 leads to aberrantly increased ER transcriptional activity." (PMID 34717714, 2021). "Using the developed highly sensitive and specific ESR1 NAPA assay, we found that 23% (3/13) of ER+ primary breast tumours harbored the Y537C ESR1 mutation." (PMID 33535614, 2021). "The estrogen receptor alpha (ER; encoded by the ESR1 gene) has been known for decades as a targetable driver of breast tumor growth." (PMID 33937624, 2021). "Approximately 75% of breast tumours is characterized by the expression of estrogen receptor alpha (ERα), encoded by the estrogen receptor 1 (ESR1) gene." (PMID 32684154, 2020). "Breast tumors are known to undergo genomic evolution, and ESR1 mutations (ESR1m) have been identified in 9–40% of patients with metastatic ER+ breast cancer resistant to aromatase inhibitors (AIs)." (PMID 32309212, 2020). "These activating ESR1 point mutations confer constitutive, hormone-independent activity of ER and are often enriched in breast tumors after aromatase inhibitor (AI) treatment." (PMID 30525098, 2018). "As ESR1 activating hotspot mutations are reported enriched in endocrine‐resistant metastatic breast tumors, we tested for any of the helix 12 activating hotspot mutations in 11 randomly selected samples from adjuvant tamoxifen‐treated patients." (PMID 29972720, 2018). "GATA3, ZNF703, and MAP3K1 are in the group 1 genes associated with acquired endocrine therapy resistance in breast tumors expressing ESR1 and ERBB2." (PMID 29738475, 2018). "Breast tumors with an ESR1 mutation, often arising after selective antiestrogen treatment pressure, may depend on constitutive ER pathway signaling and therefore remain sensitive to next-generation oral SERD therapy." (PMID 41201834, 2026).
breast tumors (continued). "In our study, higher ESR1 mRNA levels in hormone‐positive early breast tumors at the time of diagnosis were significantly associated with increased tumor size, more lymph node involvement, increased tumor stage, and a trend toward more lympho‐vascular invasion." (PMID 40666735, 2025). "ESR1 variants are also associated with specific breast tumor subtypes in GWAS." (PMID 38836758, 2024). "In addition to the mutated peptides, we also included their respective wild-type peptides to serve both as a negative control and a potential immunotherapeutic target, as ESR1 is a highly enriched tumor-associated antigen (TAA) in ER+ breast tumors." (PMID 38335301, 2024). "Mutations in the ESR1 gene were first described in 1997 but their role in endocrine resistance was not established until 2013 due to the historical practice of mainly sequencing treatment-naïve breast tumors." (PMID 38003387, 2023). "Bockers suggested that KLHL24 associated with ESR1 could act as the upstream regulator to promote breast tumor growth." (PMID 34238288, 2021). "In the present study—the largest to our knowledge—we have analyzed the RNA-seq data of 3217 primary breast tumors for ESR1 resistance mutations and, for the first time, identify the association of such mutations to clinical outcomes in the adjuvant treatment setting." (PMID 33937624, 2021). "The discovery of ESR1 gene amplifications in 1990 sparked intense interest in investigating the role of this mutational event to be a potential driver of endocrine therapy resistance and recurrent disease in ER+ breast tumors." (PMID 31106278, 2019). "Although fulvestrant is used exclusively in the metastatic setting for ER+ disease, treating primary breast tumors upfront with fulvestrant or more potent SERDs like AZD9496 may reduce the incidence of disease driven by ESR1 LBD point mutations." (PMID 31106278, 2019). "Notably, all breast tumors from patients that were found to harbor ESR1 LBD point mutations were treated with AIs." (PMID 31106278, 2019). "However, these SNPs are associated with ESR1-negative and BRCA-mutated breast tumors, suggesting an ESR1-independent linkage and pointing at CCDC170 instead." (PMID 30149579, 2018). "In addition, ESR1 is associated with aggressive breast tumor types, and KRT 19 has been implicated as a marker of circulating tumor cells." (PMID 29361610, 2018). "A resected breast tumor had the E380Q ESR1 mutation beyond the selected cut-off level." (PMID 29166868, 2017). "Consistent with this, our study has revealed that first-degree family history of breast cancer (or breast and/or ovarian cancer) may be a risk factor for breast tumors carrying the ESR1 A908G mutation." (PMID 17553133, 2007). "Characterization of breast tumors for the ESR1 A908G point mutation, shown by Fuqua and colleagues to be hypersensitive to estrogen, may reveal important etiologic clues." (PMID 17553133, 2007). "Notably, however, a somatic mutation in the ESR1 gene was identified, which is significant because breast tumors with ESR1 mutations have been shown to be resistant to letrozole both alone and in combination with other agents, including the PI3Kα inhibitor alpelisib." (PMID 38239650, 2023). "In addition, we observed changes in the expression of specific genes, including significant reductions in the expression of Rb1, Esr1, and Pgr, and increases in the expression of Erbb2, Egfr, and the genes encoding keratins 5, 6, and 17, as they are in human basal-like breast tumors." (PMID 33652981, 2021). "This may be explained by the number of primary, non‐metastatic breast tumor tissue in our sample, as the incidence of ESR1 mutations rises to 15% to 20% in metastatic ER‐positive tumors after prior endocrine treatments, suggesting the development of resistance." (PMID 32881420, 2020).
breast tumors (continued). "Also, since the ER-associated gene set was enriched in ER+ breast tumors with RD after chemotherapy, we examined whether quantitative assessment of the ER (ESR1) mRNA alone could provide the same information." (PMID 18445275, 2008). "In this real-world cohort of more than 750 patients with ESR1-mutant breast tumors, the median time-to-next-treatment on elacestrant was 6.4 months overall and 8.8 months in patients with one or fewer prior lines of metastatic therapy." (PMID 41201834, 2026). "In metastatic breast tumors harboring ESR1 mutations, selective estrogen receptor modulators (SERMs) and selective estrogen receptor covalent antagonists (SERCAs) seem to work better than AI." (PMID 40989687, 2025). "In breast tumor cells, estrogen treatment frequently induces an amplification of ESR1 gene at 6q25 locus upregulating ER protein synthesis." (PMID 39329990, 2024). "Raad S. Gitan found an increased DNA hypermethylation of the ESR1 CpG island in breast tumors compared to normal controls by methylation‐specific oligonucleotide microarray." (PMID 37881785, 2023). "To create a comprehensive map of exons and splice junctions for the ESR1 locus, we analysed RNA‐Seq data for 3478 breast tumours in combination with known splice junctions from GENCODE and RefSeq." (PMID 37676103, 2023). "Estrogen receptor alpha (ERα, encoded by ESR1) is a well-characterized transcription factor expressed in more than 75% of breast tumors and is the key biomarker to direct endocrine therapies." (PMID 35304506, 2022). "Human primary breast tumors display ESR1 promoter DNA hypermethylation that is inversely correlated with ESR1 gene expression." (PMID 36140723, 2022). "The AR and ESR1 transcript levels were evaluated by real time PCR on all the 275 breast tumor samples." (PMID 34234742, 2021). "In breast tumors and cell lines, expression of GATA3 is strongly associated with those of ESR1 and FOXA1." (PMID 34831189, 2021). "The nuclear hormone receptor and oncoprotein estrogen receptor alpha/estrogen receptor 1 (ER/ESR1) is overexpressed in around 70% of breast tumors." (PMID 34925466, 2021). "Evidence suggests that estrogen receptor alpha (ERα, encoded by ESR1), a member of the nuclear receptor family of transcription factors, is involved in the initiation and progression of ER+ breast tumors." (PMID 33980285, 2021). "Genomic profile analysis revealed various genomic mutations in primary breast tumors, including those of PIK3CA, AKT1, estrogen receptor 1 (ESR1), and checkpoint kinase 2, and more frequent mutations in metastatic lesions." (PMID 33672204, 2021). "This review recapitulates the current body of knowledge on the structure of the ESR1 gene and the complex mechanisms controlling its expression in breast tumors." (PMID 34831189, 2021). "CREBBP, EP300, ESR1, GATA3, and MYC are well-known genetic biomarkers and mutate frequently in breast tumors." (PMID 34235216, 2021). "Concordantly, elevated ESR1 expression was enriched in ER+ breast tumors (fourth panel, yellow), but many expressed relatively low levels of ESR1 (fourth panel, blue vs. yellow)." (PMID 33291647, 2020). "Taken together, these results suggest that downstream ER kinases such as CDK4/6 as well as transcriptional coregulators such as the 26S proteasome are attractive therapeutic targets to treat ESR1 fusion positive, metastatic breast tumors." (PMID 31106278, 2019). "Despite the relatively high frequency of elevated ESR1 copy numbers in breast tumors, the clinical relevance of ESR1 gene amplification as a prognostic or predictive biomarker is not clear and requires further study." (PMID 31511774, 2019).